PPP1CC (protein phosphatase 1 catalytic subunit gamma)
Description:
Protein phosphatase that associates with over 200 regulatory proteins to form highly specific holoenzymes which dephosphorylate hundreds of biological targets. Protein phosphatase 1 (PP1) is essential for cell division, and participates in the regulation of glycogen metabolism, muscle contractility and protein synthesis. Dephosphorylates RPS6KB1. Involved in regulation of ionic conductances and long-term synaptic plasticity. May play an important role in dephosphorylating substrates such as the postsynaptic density-associated Ca(2+)/calmodulin dependent protein kinase II. Component of the PTW/PP1 phosphatase complex, which plays a role in the control of chromatin structure and cell cycle progression during the transition from mitosis into interphase. In balance with CSNK1D and CSNK1E, determines the circadian period length, through the regulation of the speed and rhythmicity of PER1 and PER2 phosphorylation. May dephosphorylate CSNK1D and CSNK1E (By similarity). Regulates the recruitment of the SKA complex to kinetochores. Dephosphorylates the 'Ser-418' residue of FOXP3 in regulatory T-cells (Treg) from patients with rheumatoid arthritis, thereby inactivating FOXP3 and rendering Treg cells functionally defective. Together with PPP1CA (PP1-alpha subunit), dephosphorylates IFIH1/MDA5 and RIG-I leading to their activation and a functional innate immune response. Core component of the SHOC2-MRAS-PP1c (SMP) holophosphatase complex that regulates the MAPK pathway activation. The SMP complex specifically dephosphorylates the inhibitory phosphorylation at 'Ser-259' of RAF1 kinase, 'Ser-365' of BRAF kinase and 'Ser-214' of ARAF kinase, stimulating their kinase activities. Dephosphorylates MKI67 at the onset of anaphase. The SMP complex enhances the dephosphorylation activity and substrate specificity of PP1c.
Synonyms: PP-1G; PP1C; PP1gamma; PPP1G
Tractability: Small molecule: a structure with a bound ligand is known. PROTAC: ubiquitination databases record sites on it; its protein half-life has been measured; a small molecule that binds it is known.
Target class: Protein Phosphatase; Phosphatase; Serine/threonine protein phosphatase; Enzyme
Chemical probes: PD070600
Gene: Protein-coding gene on chromosome 12 (110,719,680 to 110,742,939, reverse strand). Ensembl gene ENSG00000186298.
Subcellular location: Cytoplasm; Nucleus; Nucleus, nucleolus; Nucleus, nucleoplasm; Nucleus speckle; Chromosome, centromere, kinetochore; Cleavage furrow; Midbody; Mitochondrion; Cytoplasm, cytoskeleton, microtubule organizing center
Subcellular location (Human Protein Atlas): Cytosol; Nucleoplasm; Vesicles
Pathways (Reactome):
Cell Cycle: Amplification of signal from unattached kinetochores via a MAD2 inhibitory signal; EML4 and NUDC in mitotic spindle formation; Mitotic Prometaphase; Resolution of Sister Chromatid Cohesion; Separation of Sister Chromatids
Disease: Gain-of-function MRAS complexes activate RAF signaling; Maturation of hRSV A proteins; SHOC2 M1731 mutant abolishes MRAS complex function
Signal Transduction: Downregulation of TGF-beta receptor signaling; RAF activation; RHO GTPases Activate Formins
Circadian clock: Phosphorylation and nuclear translocation of the CRY:PER:kinase complex
Metabolism: Triglyceride catabolism
Gene Ontology:
Molecular function: protein binding; protein kinase binding; protein serine/threonine phosphatase activity; RNA binding; phosphatase activity; phosphoprotein phosphatase activity; hydrolase activity; lamin binding; protein domain specific binding; protein phosphatase 1 binding; protein phosphatase binding; protein-containing complex binding
Biological process: protein dephosphorylation; regulation of circadian rhythm; circadian regulation of gene expression; entrainment of circadian clock by photoperiod; MAPK cascade; mitotic sister chromatid segregation; neuron differentiation; positive regulation of Ras protein signal transduction; positive regulation of glial cell proliferation
Cellular component: chromosome, telomeric region; cleavage furrow; cytoplasm; cytosol; focal adhesion; midbody; mitochondrion; nuclear speck; nucleolus; nucleoplasm; nucleus; protein phosphatase type 1 complex; protein-containing complex; PTW/PP1 phosphatase complex; dendritic spine; glutamatergic synapse; microtubule organizing center; mitochondrial outer membrane; postsynapse; presynapse
Genetic constraint (gnomAD): Loss-of-function variants: 10 observed, 29.08 expected, observed/expected ratio (o/e) 0.34, 90% interval 0.21 to 0.58. The upper end of that interval is the gene's LOEUF score, 0.58, which puts it in group 2 of 6, group 1 being the genes least tolerant of losing a copy. Missense variants: 150 observed, 348.18 expected, observed/expected ratio (o/e) 0.43, 90% interval 0.38 to 0.49. Synonymous variants: 144 observed, 124.87 expected, observed/expected ratio (o/e) 1.15, 90% interval 1.01 to 1.32.
Homologues: Orthologues: mouse Ppp1cc (99% identical), tropical clawed frog ppp1cc (99% identical), zebrafish ppp1cc (98% identical), pig PPP1CC (95% identical), Caenorhabditis elegans ZK938.1 (52% identical), Caenorhabditis elegans F23B12.1 (50% identical), Caenorhabditis elegans F25B3.4 (49% identical), Caenorhabditis elegans C47A4.3 (47% identical), Caenorhabditis elegans Y71G12B.30 (47% identical), Caenorhabditis elegans ZK354.9 (46% identical), Caenorhabditis elegans C25A6.1 (46% identical), Caenorhabditis elegans C23G10.1 (45% identical), and 17 more. Paralogues in human: PPP1CA (93% identical), PPP1CB (89% identical), PPP2CB (46% identical), PPP2CA (45% identical), PPP4C (45% identical), PPP6C (42% identical), PPP3CA (40% identical), PPP3CB (40% identical), PPP3CC (40% identical), PPP5C (35% identical), PPEF2 (34% identical), PPEF1 (33% identical).
Diseases named in the same sentence as PPP1CC in open-access papers:
PPP1CC is named in the same sentence as 35 diseases in open-access papers, as found by Europe PMC text mining. Sharing a sentence is not in itself a finding about the gene and the disease. The quoted sentences say what the papers report.
male infertility (3 papers, 2012 to 2024). The inability of the male to effect fertilization of an ovum after a specified period of unprotected intercourse. "Deletion of the Ppp1cc gene causes loss of both isoforms resulting in oligo-terato-asthenozoospermia and thus, causing male infertility due to impaired spermiogenesis." (PMID 39135778, 2024). "Although PPP1CC1, the other Ppp1cc product, is expressed in many tissues including testis, the only phenotype resulting from deletion of Ppp1cc gene is male infertility." (PMID 23082183, 2012). "The only phenotype resulting from the knockout of Ppp1cc is male infertility." (PMID 31921853, 2019). "Since, PP1γ2 is the predominant isoform in testis, it strongly suggests, but does not prove that the reason for male infertility in mice lacking Ppp1cc is likely due to the absence of only PP1γ2 in differentiating spermatogenic cells." (PMID 31921853, 2019).
liver cancer (2 papers, 2021 to 2023). An epithelial or non-epithelial malignant neoplasm that arises from the liver. "RNF12 might interact with PPP1CC to promote the progression of liver cancer by regulating the signalling pathway." (PMID 37132043, 2023). "Next, we analyzed the expression levels of ACTG1, CSNK1D, PPP1CC, and BIRC5 in HCC tissue samples in normal liver (n = 160) and liver cancer (n = 369) samples from the GEPIA dataset." (PMID 33816607, 2021).
ovarian carcinoma (2 papers, 2019). A malignant neoplasm originating from the surface ovarian epithelium. "BRCA1, CDKN1B, PPP1CC, SKP2, and URI1 were clustered in subnetwork 8 and categorized as shared proteins in PCOS and ovarian cancer, hence suggesting an association between the two." (PMID 31216618, 2019). "In subnetwork 8, long-term potentiation was identified as a significant pathway, where PPP1CC and PPP1CA directly interacted with three PCOS-ovarian cancer-shared PCOSrps—i.e., BRCA1, PPP1CC, and URI1—and indirectly interacted with two shared PCOSrps (CDKN1B and SKP2)." (PMID 31216618, 2019).
amyotrophic lateral sclerosis (1 paper, 2022). Amyotrophic lateral sclerosis (ALS) is a neurodegenerative disease characterized by progressive muscular paralysis reflecting degeneration of motor neurons in the primary motor cortex, corticospinal tracts, brainstem and spinal cord. "Employing the weighted gene co-expression network analysis (WGCNA) in a large-scale blood gene expression study on amyotrophic lateral sclerosis (ALS) patients, it has been found that PCNP shows a similarity in pattern expression to PPP1CC." (PMID 35186732, 2022).
atherosclerosis (1 paper, 2023). A disease characterized by the build-up of fatty material and calcium deposition in the arterial wall resulting in partial or complete occlusion of the arterial lumen. "Mechanically, circRNA PPP1CC directly targeted miR‐103a‐3p and miR‐107 to increase the expression of HMGB1, suggesting that circRNA PPP1CC may represent a novel therapeutic target for atherosclerosis by blocking SMCs pyroptosis." (PMID 37125240, 2023).
autism spectrum disorder (1 paper, 2025). A spectrum of developmental disorders that includes autism, and Asperger syndrome. "Notably, SH3RF2, whose single-copy knockout leads to autism spectrum disorder (ASD)-like behaviors in mice, is uniquely expressed in the striatum, forming a complex with CaMKII (an ASD-associated protein) and PPP1CC." (PMID 40890295, 2025).
breast carcinoma (1 paper, 2022). "Except for PPP1CB, PPP1CC, PPP5C and PPEF1, the mRNA expression levels of the PPPCs family in breast cancer tissues were significantly different from those in paracancerous tissues." (PMID 34964699, 2022). "PPP1CC, PPP5C and PPEF2 were not aberrantly expressed in breast cancer tissues." (PMID 34964699, 2022).
chronic myeloid leukemia (1 paper, 2025). "For example, myeloproliferative diseases (excluding chronic myeloid leukemia, CML) have the most colocalized genes, including RPN1, BRAP, PPP1CC, ERP29, and PARP1." (PMID 41048997, 2025).
colorectal cancer (1 paper, 2025). A primary or metastatic malignant neoplasm that affects the colon or rectum. "We found that NCOR1, NONO, and PPP1CC were more highly expressed in right-sided colorectal cancer, while CLDN4, EGR1, and ID2 were more highly expressed in left-sided colorectal cancer." (PMID 41174721, 2025).
diabetes (1 paper, 2024). "Additionally, GYS1 and PPP1CC have been reported to improve insulin resistance by regulating miR-140-5p in diabetes.Proteasome alpha subunits (PSMAs) have been implicated in the malignant progression of various human cancers." (PMID 38166541, 2024).
Infertility (1 paper, 2012). "Thus, infertility of Ppp1cc null males, resulting in the disruption of the spermatogenic process, particularly during mid- and late- spermiogenesis, implies that PPP1CC2 must be critical for the morphological development, spermiation, and fertility of male germ cells." (PMID 23082183, 2012).
myeloproliferative diseases (1 paper, 2025). "Moreover, myeloproliferative diseases (excluding CML) and essential (haemorrhagic) thrombocythaemia have three identical colocalized genes, namely BRAP, PPP1CC, and ERP29." (PMID 41048997, 2025).
pancreatic cancer (1 paper, 2021). "Among all the PPPcs, PPP1CB, PPP1CC, PPP2CA, PPP2CB, PPP3CB, and PPP5C had tight associations with at least one of the pancreatic cancer related genes in that list." (PMID 33270085, 2021). "In addition, only PPP3CB and PPP6C showed favorable prognostic values with regard to protein level, whereas PPP1CA, PPP1CB, PPP1CC, PPP2CA, PPP2CB, and PPP3CA showed unfavorable prognostic values in pancreatic cancer (P<0.05)." (PMID 33270085, 2021).
tumor (11 papers, 2013 to 2025). "The catalytic subunit of PP1 is encoded by PPP1CA, PPP1CB, and PPP1CC (protein name PP1γ), and the roles of each subunit in tumor development are inconsistent." (PMID 40626009, 2025). "It was notable that downstream of PPP1CC and ROCK1 was MYL9, which was a famous hallmark tumor gene." (PMID 27634882, 2016). "However, in the current study blood expression changes in HIPK2 and PPP1CC identify those participants with significant anti-tumour transcriptomic responses to supplementation in the rectum." (PMID 34340708, 2021). "While the analysis of the methylation of Spinophilin showed increased methylation, the analysis of PPPCs subunits methylation showed a decreased methylation mean, in tumors vs. non-tumor samples, in PPP1CA and PPP1CB, and increased methylation mean in PPP1CC." (PMID 29285244, 2017). "Moreover, our results showed that ACTG1, CSNK1D, PPP1CC, and BIRC5 expression was negatively correlated with miR-497-5p expression in HCC tumor biopsies (n = 364, r = −0.32, -0.29, -0.24, and -0.33, respectively, p < 0.001)." (PMID 33816607, 2021). "Further analysis of the correlation of the expression level of the prognostic genes with age, gender, tumor stage and tumor grade of HCC patients showed that the expression of FYN, PPP1CC, RAC1, and SPP1 was significantly correlated with the tumor grade (P < 0.05)." (PMID 33850056, 2021). "In addition, the expression of PPP1BC, PPP1CC and RAC1 was correlated with the tumor stage (P < 0.05); the expression of PPP1CC and SPP1 was correlated with age (P < 0.05); the expression of PPP1CB was correlated with gender (P < 0.05)." (PMID 33850056, 2021). "However, the analysis of LSCC specimens did not reveal significant correlations of either PPP3R1 or PPP1CC with the prognosis or tumor malignancy (data not shown), while an increased PIK3CD expression was significantly correlated with tumor progression and the clinical outcomes." (PMID 32555190, 2020).
cancer (8 papers, 2018 to 2025). A tumor composed of atypical neoplastic, often pleomorphic cells that invade other tissues. "Functional gene clusters shared among cancer types include DYNC1LI2/I2/H1 that encode different components of the cytoplasmic dynein 1 complex and PPP1CC/1CA/2CB/2CA that encode subunits of protein phosphatase enzymes." (PMID 34620211, 2021). "We found that FYN and PPP1CB were negatively correlated with RNAss, while PPP1CC was positively correlated with RNAss, which indicated that prognostic genes might have a relationship with cancer cell sensitivity or resistance to chemotherapy treatment." (PMID 33850056, 2021). "Furthermore, increased PPP1CC and FYN expression was correlated with increased drug sensitivity to cancer cells, such as PX−316, Ifosfamide, okadaic acid, Chelerythrine, AT-13387, and Amonafide (cor > 0.29 and P < 0.05)." (PMID 33850056, 2021). "To determine whether MYC and its putative interactor, PP1/PNUTS, are both expressed in cancer, we examine the amplification status of the MYC gene, as well as genes of the PP1/PNUTS holoenzyme (PPP1CA, PPP1CB, PPP1CC, and PPP1R10) in The Cancer Genome Atlas (TCGA) datasets." (PMID 30158517, 2018).
infection (2 papers, 2014 to 2018). The state of being infected such as from the introduction of a foreign agent such as serum, vaccine, antigenic substance or organism. "In agreement with the MS data, infection with H. pylori or 10 min of treatment with cytokines led to the dissociation of PPP1CA, PPP1CB and PPP1CC from TAK1." (PMID 29581850, 2018).
PPP1CC also shares sentences with these, for which no sentence is quoted: prostate carcinoma (3 papers); asthenozoospermia (2); viral infection (2); Alzheimer disease (1); cardiovascular disease (1); cognitive decline (1); COVID-19 (1); esophageal cancer (1); esophageal squamous cell carcinoma (1); glioma (1); hepatocellular carcinoma (1); Insulin resistance (1); lymph node metastasis (1); melanoma (1); metastasis (1); nasopharyngeal carcinoma (1); pancreatic adenocarcinoma (1); Parkinson disease (1); thrombocythaemia (1).